INS (insulin)
Diseases named in the same sentence as INS in open-access papers (continued):
Sharing a sentence is not in itself a finding about the gene and the disease.
diabetes (continued). "However, significant differences were observed between the initial examination and the examination 2 hours after the surgery in insulin-treated patients with or without diabetes." (PMID 25278226, 2014). "Epidemiological evidence suggests an increased risk of developing dementia, including Alzheimer’s disease, in persons with obesity, type 2 diabetes, but also in those with poor insulin sensitivity without diabetes, suggesting a mechanistic link between adiposity, insulin sensitivity and dementia." (PMID 23896654, 2013). "If UCPCR can be used in people without diabetes this practical method could allow a large scale, population-based assessment of insulin resistance without needing a blood sample to be taken." (PMID 24353253, 2013). "Furthermore, although IPC is not efficient in STZ-diabetes, the intrinsic cardioprotective capacity is present and can be triggered by insulin." (PMID 23922853, 2013). "Even in elderly individuals without diabetes, postprandial hyperglycemia occurs because of a delay in insulin secretion in response to feeding and may contribute to an increase in the number of elderly diabetic patients." (PMID 23302697, 2013). "Thus, although this pilot clinical study did not involve patients with diabetes, we still monitored blood glucose, insulin and lipid levels of study subjects." (PMID 23700406, 2013). "This phenomenon could be related to the action of sarcoplasmic reticulum Ca2+ ATPase (SERCA) whose levels have been shown to be increased in early diabetes and especially stimulated by the presence of insulin but were not evaluated in this work." (PMID 23530768, 2013). "Thus, for 34 years the only available glucose-lowering drug was insulin, irrespective of diabetes type." (PMID 24348585, 2013). "Indeed, recent comparative studies examining the pharmacokinetic and pharmacodynamic profiles or the efficacy and safety of ILPS with the other two long-acting insulin analogues suggest that ILPS has a similar glycemic control to glargine and detemir in type 2 diabetes mellitus, out of pregnancy." (PMID 23840206, 2013). "The discovery of SGLT2 inhibitors, with novel mechanism independent of insulin secretion or sensitization, may possibly expand the armamentarium in the battle against type 2 diabetes mellitus." (PMID 24341330, 2013). "No patients in either group took any anti-diabetes drugs or insulin injections." (PMID 24223115, 2013). "According to our experience, we suggest that women with GDM showing clinical features as no family history of diabetes, normal pre-pregnancy BMI, need for insulin therapy in the early weeks of pregnancy, and age higher than 35 years, shall be preferably tested for autoimmunity." (PMID 23606858, 2013). "Overall excess mortality remained high in people with diabetes; in 2003–2007 RRs in the non-insulin treated was 1.82 for men and 1.95 for women and in the insulin treated 3.45 and 4.29, and excess coronary heart disease mortality in the insulin treated: RR was 4.71 in men and 7.80 in women." (PMID 23837500, 2013). "Therefore, we have examined the Mg levels in the serum and urine of Northeast Chinese population at different categories of insulin sensitivity (metabolic syndrome) and diabetes with and without diabetic complications." (PMID 23418599, 2013). "The 7-iF is broadly based on the EMGQN guidelines but, unlike the latter, it includes T1D autoimmune markers and insulin treatment in the attempt to exclude patients with type 1 diabetes, which is the most prevalent form of diabetes (> 80%) in young individuals." (PMID 24244580, 2013). "Moreover, increased MDA level in the liver clearly indicates the role of oxidative stress in diabetes, and AEHE might reduce lipid peroxidation by modulating glucose/insulin system." (PMID 24090482, 2013). "Additionally, data suggested the anti-diabetes activity of L. gasseri BNR17 may be to due elevated GLUT4 and reduced insulin levels." (PMID 23382926, 2013).
diabetes (continued). "In addition, in subjects without established diabetes, visceral fat adjacent to the aorta seemed to exert effects on insulin resistance and systemic inflammation." (PMID 24499326, 2013). "Thus, whether measured against the degree of obesity or IR, the data indicates a close relationship between defective response to insulin of p42/44 MAPK activity in muscle and the clinical measures of pre-diabetes." (PMID 23468892, 2013). "Furthermore, IRS-2(−/−) mice have confirmed that insulin signalling defects in the liver, but not in skeletal muscle or adipose tissue, play a major role in the development of diabetes, particularly in combination with pancreatic β cell dysfunction." (PMID 23560040, 2013). "We also established that the fasting glucose and insulin levels were raised in obese subjects despite having no complaints or symptoms of diabetes, these levels along with HOMA-IR showed a strong positive correlation with chemerin, while QUICKI had a negative correlation." (PMID 23468920, 2013). "However, evidence from previous studies suggests that for non-critically ill type 1 diabetic patients, insulin therapy initiated in the hospital does not yield improved metabolic outcomes when compared to diabetes care initiated in an outpatient setting." (PMID 23587308, 2013). "The PI3K/AKT signaling pathway is important for insulin signaling and glucose metabolism, lymphocyte migration, proliferation, and differentiation, and TGF-β signaling regulation, making it an important therapeutic target for the treatment of cancer, diabetes, and other diseases." (PMID 23506302, 2013). "These pregnant women shared certain characteristics, that is, no family history of diabetes, age over 35 years, normal prepregnancy BMI, need for insulin therapy as of the early weeks of pregnancy, high-titer anti-GAD antibody positivity, and low fasting plasma C-peptide levels." (PMID 23606858, 2013). "MC4R knockout (KO) rats are obese and profoundly insulin resistant without frank diabetes." (PMID 24400148, 2013). "Furthermore, there is no doubt that insulin is neurotrophic in moderate concentration, but the whole circumstances become more complicated in conditions of hyperinsulinism in diabetes." (PMID 24386004, 2013). "However, the excess overall mortality rate showed no change for those with insulin-treated diabetes." (PMID 23837500, 2013). "However, this process is disrupted in people with diabetes, who either have too few pancreatic beta cells (type 1 diabetes) or do not respond appropriately to insulin (type 2 diabetes)." (PMID 24252877, 2013). "Moreover, we assume that no patient is prescribed a drug for chronic conditions such as insulin without a serious indication of diabetes." (PMID 24172142, 2013). "In addition, the mean duration of diabetes history among patients taking insulin therapy was longer than those not taking insulin therapy (11.7 years versus 5.5 years)." (PMID 24260140, 2013). "“I never had anything against insulin but I could not seeing myself to inject insulin” (4 years of insulin use/ 10 years of having diabetes)." (PMID 24164794, 2013). "Pancreas transplantation alone (PTA) is restricted to patients with good renal function who suffer from brittle diabetes or frequent hypoglycemia; this is the only treatment option allowing non-uremic patients with brittle diabetes long-term insulin-independency." (PMID 23816330, 2013). "I dared not” (2.5 years of insulin use/ 6 years of having diabetes)." (PMID 24164794, 2013). "By upregulating insulin secretion and the degree to which individuals are capable of achieving this determines whether or not an individual develops diabetes." (PMID 23542897, 2013). "Analysis pooling data from control and subjects with pre-diabetes showed that BMI, waist circumference, fasting and postprandial plasma glucose, fasting serum insulin, and HOMA-IR were all higher in subjects without the A allele than in those with the A allele." (PMID 23431394, 2013).
diabetes (continued). "Dysfunctionality in either peripheral or hepatic insulin sensitivity will contribute to the metabolic disturbance observed in subjects with impaired glucose tolerance (IGT), diabetes mellitus (DM), or the metabolic syndrome." (PMID 24363940, 2013). "For people with insulin-treated diabetes, the excess overall mortality in 2003–2007 was more than threefold among men and fourfold among women compared to the people without diabetes." (PMID 23837500, 2013). "After 2 weeks of diabetes, there were no insulin-positive cells remaining to measure." (PMID 23762878, 2013). "It is possible that some of these patients may have been recently diagnosed with diabetes and may not have progressed to having diabetes complications or to require insulin for good glycaemic control." (PMID 24349036, 2013). "The three groups with lower insulin secretion after oral glucose load are NGT and IFG (who have no problems disposing of the load) and T2DM (who may show relative secretion insufficiency, and for this reason show the frank clinical picture of diabetes)." (PMID 24009656, 2013). "Previous studies have suggested that women without diabetes may be more insulin sensitive compared with men, which could drive the development of CAC and CVD over time." (PMID 23341938, 2013). "It is common knowledge that insulin therapy is not obligatory for patients with type 2 diabetes, but in these patients it is often necessary in progressive insulinopenia, prolonged duration of diabetes, and very poor glycemic control." (PMID 24363502, 2013). "Baker stated that statins do not appear to demonstrate a 'class effect' on insulin sensitivity in patients without diabetes, based on meta-analysis of 16 trials comparing pravastatin, simvastatin, atorvastatin and rosuvastatin to placebo or controls in non-diabetic patients." (PMID 23951249, 2013). "However, after 6 months of induction of diabetes, rat pancreas showed the appearance of small well formed islets and positive insulin cells but no CD105 positive cells." (PMID 24279645, 2013). "In summary, the literature presents incontestable data that the gut microbiota and its modulation by nutrients and excessive energy intake heavily influence glucose metabolism, lipid storage, inflammation, and insulin activity in a negative way, as observed in obesity and diabetes." (PMID 23840101, 2013). "The Indian Diabetes Prevention Programme (IDPP) showed that progression to DM from impaired glucose tolerance (IGT) can be prevented by 28.5% with LSM and 26.4% with with metformin (MET) in individuals who were younger, leaner, and more insulin resistant as compared with the control group." (PMID 23573413, 2013). "Insulin therapy is not always necessary as diabetes may respond to oral sulphonylureas but, if needed, insulin doses required are lower than in patients with T1D." (PMID 24051999, 2013). "Although significant improvement in the blood sugar profile occurred, low-dose insulin was still needed for diabetes control in patient 2, indicating that thiamine treatment may not fully correct the lack of insulin." (PMID 24072090, 2013). "Similarly, among 84 SGA children participating in the US SGA trial from the KIGS Database, a reduction in insulin sensitivity occurred during GH treatment, but no patients developed impaired glucose tolerance or overt diabetes mellitus." (PMID 22559301, 2012). "Diabetes mellitus (DM) is a serious metabolic disorder of glucose homeostasis reflecting destruction of the β-cells of the pancreas and subsequent lack of insulin production (type 1 DM, T1DM) or decreased target organ sensitivity to insulin and β-cell dysfunction (type 2 DM, T2DM)." (PMID 23087692, 2012). "In summary, our results suggest that targeting p/CIP and SRC-1 may not only reduce obesity but also enhance glucose uptake and insulin sensitivity, which would offer benefits not obtained by using TZDs for treatment of diabetes." (PMID 22859932, 2012).
diabetes (continued). "The damage can be prevented by controlling diabetes and blood sugar, although once occurred not all damage can be reversed; in fact, some alterations in gene expression engendered by diabetes are not reversed even by long-term control of blood sugar by insulin." (PMID 23372421, 2012). "However, there have been continuous references in the scientific literature to the presence of insulin in milk and the presence of elevated levels in the milk of mothers with diabetes compared to mothers without diabetes." (PMID 22500167, 2012). "However the relationships seen, although weaker, remains when analysing our results by type of diabetes suggesting the relationship between insulin secretion and glucose response is not due to differences between diabetes subtypes alone." (PMID 22681724, 2012). "Similarly in the study by Bakari, fasting plasma insulin did not correlate with duration of diabetes." (PMID 22738260, 2012). "However, in the study no OGTT-based indices of insulin sensitivity or beta-cell function were found to be predictors of diabetes development." (PMID 23185618, 2012). "One could speculate that some knock-outs procedures may alter the physiology of insulin-glucagon interactions, and may reflect a metabolic system not seen in physiology or in diabetes." (PMID 22969729, 2012). "Females with diabetes often inject insulin through the clothing, without exposing their skin." (PMID 23497693, 2012). "Moreover, removal of VF in Zucker Diabetic Fatty (ZDF) rats prevented the progressive decrease in insulin action and delayed the onset of diabetes, but VF extraction did not alter plasma free fatty acid levels." (PMID 22675349, 2012). "Duration of diabetes when starting insulin was generally around 10 years, but it is not possible from the current study to know how long uncontrolled hyperglycaemia had been allowed to persist before starting insulin, nor what other therapeutic attempts had been made to control it." (PMID 22519930, 2012). "One could hypothesize that in diabetes, in absence of the tonic effect of insulin, islet α-cells are oversensitive to insulin and are exposed to increased somatostatin." (PMID 22969729, 2012). "Diabetes mellitus, often simply referred to as diabetes--is a group of metabolic diseases in which a person has high blood sugar, either because the body does not produce enough insulin, or because cells do not respond to the insulin that is produced." (PMID 22257465, 2012). "Diabetes is characterized by hyperglycaemia due to absolute or relative lack of insulin." (PMID 23094067, 2012). "Indeed, evidences have shown that the benefits of exercise training per se on glycemia control in type 1 diabetes mellitus without insulin therapy is limited." (PMID 23285277, 2012). "Treatment with insulin is not indicated for any other disease than diabetes mellitus." (PMID 23186328, 2012). "In patients with type 2 diabetes mellitus, the pancreatic IL1-receptor antagonist (IL-1Ra) expression is reduced and high glucose concentrations induce IL-1 production in β-cells leading to impaired insulin secretion, decreased cell proliferation, and apoptosis." (PMID 22523672, 2012). "In the present study patients with type 2 diabetes did not have significantly reduced CFR, although with a larger study population there might have been a difference, but insulin sensitivity was strongly correlated with CFR, indicating pre-diabetes microvascular damage." (PMID 22889317, 2012). "All adult patients, over 18 years old who had undergone open-heart surgery with blood glucose level >180 mg/dl (10 mmol/l) and needed insulin therapy, with or without comorbidities will be eligible for inclusion, except those patients who developed diabetes ketoacidosis." (PMID 24764523, 2012). "Because of a less efficient insulin response, non-obese diabetes patients may respond to high GL diets with more severe hyperglycemia and higher CVD risk." (PMID 22927948, 2012).
diabetes (continued). "However, further examinations showed that despite consuming oral medicines for diabetes, in some cases the level of blood sugar was not controlled; hence, the doctor either increased the number of pills or advised the consumption of insulin." (PMID 23497621, 2012). "This may be explained because the diabetes patients in our study were well controlled with either insulin or oral hypoglycemic drugs; moreover, no diabetic complications were encountered in our studied group." (PMID 23206927, 2012). "In addition, in the private sector, where there was a lack of resources, some pharmaceutical companies employed diabetes educators to assist the doctors in educating patients about insulin therapy." (PMID 22545648, 2012). "Another potential pitfall could be that the medications were grouped as acetaminophen, antiepileptics (irrespective of the type of medication), and insulin as a proxy for diabetes." (PMID 23056376, 2012). "The discrepancy may be explained by the duration of the diabetes, metabolic control, or the presence or absence of insulin treatment." (PMID 22988451, 2012). "We hypothesized that fasting serum C‐peptide level is a better marker of insulin resistance than insulin level alone and would be useful in the prediction of death related to cardiovascular disease in adults without diabetes." (PMID 23316320, 2012). "Several popular classes of oral diabetes therapies on the market include sulfonylureas, peroxisome proliferator-activated receptor-γ (PPAR-γ) agonists, metformin and so forth, which lower glucose by increasing glucose metabolism either via enhanced insulin secretion or improved insulin sensitivity." (PMID 22837677, 2012). "The Medtronic MiniMed Veo pump, available in Europe, Australia, and Canada, suspends basal insulin delivery for two hours if the sensor glucose is below a set level and the individual with diabetes fails to respond or the sensor glucose remains low for a given amount of time." (PMID 23098076, 2012). "We studied for the first time the differences in insulin signalling and inflammatory pathways in blood and visceral adipose tissue (VAT) of 20 lean healthy donors and 40 equal morbidly obese (MO) patients classified in high insulin resistance (high IR) degree and diabetes state." (PMID 23110196, 2012). "Maintaining serum glucose ≤180 mg/dL with continuous insulin infusions in patients with and without diabetes mellitus reduces morbidity and mortality, lowers the incidence of sternal wound infections, reduces hospital length of stay, and enhances long-term survival." (PMID 23209941, 2012). "Additionally, two of 4 patients with diabetes mellitus had not yet been treated, and insulin treatment was started for surgery." (PMID 22645672, 2012). "Some were not aware of the natural progression of diabetes and the need for insulin eventually." (PMID 22469132, 2012). "The pancreas ß cells may then be progressively destroyed, leading to C-peptide negative diabetes and requiring insulin therapy besides iron depletion." (PMID 22284844, 2012). "Diabetes mellitus is a group of metabolic diseases that has been classified as a disease of glucose overproduction by tissues without enough insulin production, or a disease resulting from cells not responding to the insulin in human body." (PMID 22685582, 2012). "Similarly, restricting the analysis to participants with an age at diabetes diagnosis above 40 years (N = 4901), or to participants not using insulin (N = 4809), did not affect our conclusions." (PMID 22927948, 2012). "To determine the relationship between serum concentrations of uric acid and insulin secretion with hyperglycaemic clamp technique among adults with type 2 diabetes mellitus (DM2) without hyperuricemia, we carried out a cross-sectional study on 45 patients of both gender." (PMID 22216028, 2011).